HMGB1 (high mobility group box 1)
Diseases named in the same sentence as HMGB1 in open-access papers (continued):
Sharing a sentence is not in itself a finding about the gene and the disease.
tumor (continued). "During this process, dying tumor cells release damage-associated molecular patterns (DAMPs), including high-mobility group box 1 (HMGB1) and heat-shock proteins (e.g., HSP70), which serve as endogenous danger signals." (PMID 41374974, 2025). "Further, inhibition of HMGB1 causes dramatic remodeling of the tumor microenvironment in breast cancer cells." (PMID 40959280, 2025). "Particularly noteworthy is the robust positive correlation between TIGD1 and HMGB1 expression across nearly all tumor types, along with significant associations with ICAM1, CCL5, and TNFRSF18 in the majority of cancers." (PMID 40565566, 2025). "When tumor cells are mechanically disrupted, they release unaltered tumor antigens along with molecules such as calreticulin, HMGB1, and ATP, collectively called damage-associated molecular patterns (DAMPs)." (PMID 41458348, 2025). "HMGB1 exhibits opposing functions in tumor‐associated contexts, including pro‐inflammatory and anti‐inflammatory effects within the tumor microenvironment, as well as contradictory roles in DNA damage repair and chemoresistance." (PMID 41354099, 2025). "Previous studies have demonstrated that the release of proinflammatory factors, including HMGB1, during pyroptotic cell death can trigger an anti‐tumor immune response by increasing tumor‐associated T cell infiltration." (PMID 37985644, 2024). "Preliminary examination of a few NSCLC patient samples suggested a relationship exists between serum HMGB1 and tumor-associated PD-L1." (PMID 39100092, 2024). "During tumor formation, hepatitis B virus-encoded X protein (HBx) induced HMGB1 expression, which activates signal transducer and activator of transcription 3 (STAT3) to promote EMT and angiogenesis." (PMID 38725632, 2024). "In this review, provide an overview of the diverse functions of the HMGB1/RAGE axis in tumor development and delve into the associated signaling pathways, aiming to illustrate its potential role in tumorigenesis and therapeutic intervention." (PMID 38529373, 2024). "HMGB1 expression was associated with lymphatic invasion and a lower proportion of well-differentiated tumours." (PMID 38353760, 2024). "HMGB1 can induce the maturation of DC and promote the processing/presentation of tumor antigens in association with surface major histocompatibility (MHC)-I molecules." (PMID 39231199, 2024). "The resulting tumor cell lysis releases damage-associated molecular patterns (DAMPs) such as ATP, HMGB1, and CRT, which activate innate immunity and amplify antitumor responses." (PMID 39850905, 2024). "HMGB1, which was previously reported as a kind of DAMPs in regulating inflammation, has also been associated with tumor progression now, gradually attracting researchers’ more attention." (PMID 38576043, 2024). "In summary, GPR65 on tumor-associated macrophages responds to lactate stimulation, leading to HMGB1 secretion through the cAMP-PKA-CREB signaling pathway." (PMID 38576043, 2024). "NIR-715 induced ICD-associated HMGB1 release in vitro and anti-tumor immune responses, including increased cytotoxic T lymphocyte (GZMB+ CD8+ T cell) infiltration and decreased numbers of exhausted T lymphocytes (PD-L1+ CD8+ T cell)." (PMID 39695072, 2024). "Autophagy is closely associated with drug resistance in malignant tumors, and HMGB1 can regulate the survival of tumor cells by inducing autophagy." (PMID 37897664, 2024). "The innate immune response is first triggered when dying tumor cells release damage-associated molecular patterns, such as intracellular adenosine triphosphate (ATP) and High Mobility Group Box 1 (HMGB1) protein." (PMID 39451782, 2024). "CuP/Er releases DAMPs like CRT, HMGB‐1, and ATP, which in combination with tumor‐associated antigens (TAAs), promote APC maturation and antigen presentation to T cells." (PMID 38477411, 2024).
tumor (continued). "High mobility group box-1 protein (HMGB1), phosphatidylethanolamine, and calreticulin are among damage associated molecular patterns (DAMPs) released by ferroptosis of tumor cells, which encourage DCs maturation and antigen presentation." (PMID 38853203, 2024). "Taken together, these findings confirmed the significant immunoadjuvant role of HMGB1 release from dying tumour cells and its interaction with associated PRR TLR4 on APCs as part of ICD." (PMID 38353760, 2024). "HMGB1 levels in dying tumor cells indicated that CDDP alone or the C + D treatment caused elevated levels of HMGB1 in tumor cells." (PMID 39090653, 2024). "In the early stages of ferroptosis, tumor cells release damage-associated molecular patterns (DAMPs), such as high-mobility group box 1 (HMGB1) and ATP." (PMID 39850905, 2024). "To further validate the role of HMGB1, especially phosphorylated HMGB1, in promoting tumor cell migration, we constructed an HMGB1-OE vector and an HMGB1-S100-mutation-OE vector and transfected them into the HMGB1-KD-A375 stable cell line." (PMID 39039072, 2024). "We describe the mechanisms underlying the contribution of HMGB1 to tumor development, progression, and metastasis, together with its potential role as a biomarker and therapeutic target in cancer." (PMID 38725632, 2024). "Photosens-PDT can kill tumor cells by inducing ferroptosis, and dead cancer cells can release damage-associated molecular patterns (DAMPs) including calreticulin, HMGB1, and ATP to further induce ICD." (PMID 37894410, 2023). "HMGB1 serves as a damaged-associated molecular pattern (DAMP) that induces tumor angiogenesis and its development." (PMID 37210579, 2023). "For example, GSDME-mediated pyroptosis contributes to tumorigenesis and promotes tumor progression in colitis-associated colorectal cancer through the release of HMGB1." (PMID 38066523, 2023). "In cancer, HMGB1 is linked, for the first time, to tumour progression, lymph node metastases, male sex, and key biological parameters of mismatch repair protein expression and stromal immune cell phenotype." (PMID 36980751, 2023). "The activation of DR5 also promotes immunogenic cell death in some tumor cells, releasing many damage-associated molecules (DAMPs), including CRT, HMGB1, and ATP, further enhancing the immunogenicity of tumor cells." (PMID 37305685, 2023). "Noteworthily, TLR4 polymorphisms that reduce its ability to bind HMGB1 reduce tumor antigen processing and presentation by dendritic cells." (PMID 36831435, 2023). "HMGB1 expression has been associated with almost all epithelial-derived malignancies, where it can promote both pro-tumour and anti-tumour responses." (PMID 36980751, 2023). "In colorectal cancer, LPS promotes tumor formation by releasing inflammatory factors through pathways associated with HMGB1." (PMID 37828579, 2023). "Consistent with this notion, cells lacking GSDM E were insensitive to the drug combination and showed defective HMGB1 release, reduced tumor-associated T cell infiltrates, and frequent tumor re-growth after drug removal." (PMID 36674798, 2023). "As described, RAGE ligands S100A8/A9 and HMGB1 are strongly implicated in many aspects of neoplasia." (PMID 36831371, 2023). "Melanoma tumor cells release HMGB1 in response to hypoxia, which promotes M2-like tumor-associated macrophage accumulation and IL-10 production, leading to an increased tumor growth and metastasis." (PMID 36982351, 2023). "Radiation therapy induces apoptosis and necrosis in tumor cells, causing them to release danger signals, including high mobility group box 1 (HMGB1)." (PMID 36979400, 2023). "In established CRC, this subcellular HMGB1 expression profile is linked to tumour progression and, for the first time, lymph node metastases and key biological parameters of mismatch repair protein expression, male sex, and stromal immunophenotype." (PMID 36980751, 2023).
tumor (continued). "While nuclear HMGB1 acts as a tumor suppressor for its roles in chromosome stability and induction of tumor cell death, high extracellular HMGB1 expression has been associated with poor prognosis in patients with various type of cancers." (PMID 37251376, 2023). "HMGB1 has been implicated in the proliferation and migration of cancer cells, tumor-escape, and metastasis." (PMID 37511951, 2023). "The key features of chemotherapeutics-induced ICD include CRT exposure on dying tumor cells and release of damage-associated molecular patterns (DAMPs) such as HMGB1, ATP, and the most recently identified DAMP tumor DNA4." (PMID 37391428, 2023). "Despite the current results, the mechanism of HMGB1 interchange between tumor cells and tumor-associated macrophages is still unclear." (PMID 36709284, 2023). "NET-associated HMGB1 promotes tumor cell proliferation involving interaction with tumor RAGE, activating and NF-κB signaling." (PMID 37511453, 2023). "HMGB1 knockdown inhibited tumor metastasis, and HMGB1 knockdown attenuated tumor metastasis caused by circHERC1 overexpression." (PMID 37932766, 2023). "Over the years, anthracycline-induced cell death of tumor cells has been shown to cause the release soluble molecules, including HMGB1 and ATP, resulting in tumor elimination by tumor-specific T cells." (PMID 36949244, 2023). "We then considered if this dynamic HMGB1 expression profile was associated with clinical (such as age, sex, tumour site) and pathological (such as differentiation, EMVI, mismatch repair protein expression) parameters." (PMID 36980751, 2023). "Further, we report that strong cytoplasmic HMGB1 was associated with ‘immune cold’ tumours (24% versus 15% for immune cold and NOS, respectively, p = 0.029)." (PMID 36980751, 2023). "Activated DCs release the damage-associated molecular pattern known as HMGB1 (high-mobility group box 1), which stimulates T and B cell responses while inhibiting innate immune responses to tumor-derived nucleic acids." (PMID 37842234, 2023). "High pre-therapeutic and 24-h post-treatment values in serum high mobility group box 1 (HMGB1), a nucleoprotein inflammatory cytokine that triggers protective T-cell response and promotes tumor neoangiogenesis, were associated with lower OS." (PMID 36980565, 2023). "Irradiation triggered the release of damage-associated molecular patterns (DAMPs) such as HMGB1 from tumor cells, thereby activating TLR4, which was associated with M1 macrophage polarization." (PMID 37833255, 2023). "The induction of immunogenic cell death causes the release of tumor antigens as well as damage-associated molecular patterns (DAMPs) such as high mobility group box 1 (HMGB1) and adenosine triphosphate (ATP)." (PMID 37063262, 2023). "The destruction of tumors with histotripsy leads to the release of tumor antigens and damage-associated molecular patterns (DAMPs), such as high mobility group box-1 (HMGB-1), orchestrating an antitumor immune response." (PMID 37893110, 2023). "During ICD, tumor cells release damage-associated molecular patterns (DAMPs) such as calreticulin on the cell surface, secreted HMGB1, ATP molecules, HSP70, and HSP90." (PMID 38102594, 2023). "Dying tumor cells release signals engaging the immune system, such as damage-associated molecular patterns (DAMPs), including ATP or high-mobility group box-1 (HMGB1)." (PMID 37954850, 2023). "High cyto-HMGB1 levels in tumor tissues of stage III COAD patients were associated with poor distant metastasis-free survival (DMFS) and disease-free survival (DFS)." (PMID 37945630, 2023). "Pyroptosis modulates various immune cells in the tumor immune microenvironment, inflammatory damage-associated molecular patterns (DAMPs), such as ATP, HMGB1, and mtDNA, released by pyroptotic cells, play an important role in host defense." (PMID 38012150, 2023).
tumor (continued). "This is because HMGB1 is a necrosis-associated ligand, and HMGB1 release from the nucleus was only found in the area of tumor necrosis after anti-PD-1 therapy." (PMID 37567938, 2023). "Strong cytoplasmic HMGB1 expression is also associated with an ‘immune cold’ tumour microenvironment, which is associated with poor survival." (PMID 36980751, 2023). "Previous studies reported that the overexpression of HMGB1 is involved in the development and metastasis of tumors, as well as a poor prognosis by mediating tumor-associated inflammation, promoting cell migration, and facilitating angiogenesis." (PMID 35328684, 2022). "HMGB1 is also associated with resistance of tumor cells to immunotherapy, chemotherapy, and suppression of antitumor immunity via the induction of Tregs within the TME." (PMID 36233088, 2022). "Excessive production of HMGB1 causes chronic inflammatory responses, mediated by the release of cytokines such as IL-6 and IL-8 which, in turn, stimulate carcinogenesis through tumor cell proliferation, angiogenesis, EMT, invasion, and metastatization." (PMID 36012593, 2022). "In CAC, activation of GSDME causes pyroptosis and the release of HMGB1 inducing tumor cell proliferation and proliferating cell nuclear antigen (PCNA) expression through the ERK1/2 pathway and further promoting the development of CAC." (PMID 35411030, 2022). "Through the production of PAMPs and DAMPs (such as HMGB1) that operate on Toll-like receptors, an oncolytic viral infection of tumor cells causes ICD and an I-IFN response." (PMID 35488303, 2022). "Other proteins such as G antigen 7, High mobility group protein B1 (HMGB1), Glycogen synthase, G antigen 2B/2C, and Cilia- and flagella-associated protein 44 were specifically found only in the necrotic/fibrotic tumor region." (PMID 36536419, 2022). "Tumor-associated immune cells, as well as cancer cells themselves, can release high levels of the alarmin, HMGB1, within the TME of a wide variety of malignancies." (PMID 35727208, 2022). "Granzyme B activates GSDME which is widely expressed on CD19 positive malignant B cells, resulting in tumor cell pyroptosis and the release of danger associated molecular patterns (DAMPs), such as high-mobility group box 1 (HMGB1)." (PMID 35757715, 2022). "When an extrinsic factor (e.g., cerebral cortical dysplasia, tuberous sclerosis complex, trauma, tumor) causes cell damage or death, HMGB1 is passively released from the intracellular space to the extracellular space." (PMID 35837232, 2022). "High-mobility group box 1 (HMGB1) is highly expressed in tumor cells and associated with tumor proliferation." (PMID 36003395, 2022). "HMGB1 levels have also been found to be significantly higher in human patient samples and associated with tumor differentiation and optic nerve invasion." (PMID 35269741, 2022). "The results first suggested the correlation between HMGB1 expression and the estimated infiltration value of cancer‐associated fibroblasts in certain tumours, including the TCGA tumours of BRCA‐LumA, HNSC_HPV‐, MESO and TGCT." (PMID 35765707, 2022). "In tumors, TIM-3 competes with nucleic acids in binding HMGB1, highly expressed in tumor-infiltrating DCs, and in reducing their transport to the endosomes, thereby mitigating the innate immune response to tumor-associated nucleic acid." (PMID 36551630, 2022). "Anti‐PD‐L1‐DOX‐R848‐MIP‐3α/TKNP caused maximum exposure of CRT and HMGB1 release in the tumor zone which is further confirmed by the strong green fluorescence." (PMID 37693071, 2022). "CRT translocation is regarded as an indispensable mediator of ICD, alongside vesicular release of ATP and release of high-mobility group box 1 (HMGB-1) but also secretion of type I interferons, release of annexin A1 and tumor-associated nucleic acids." (PMID 35563257, 2022). "The serum level of HMGB1 is significantly associated with tumor size, depth of invasion, and lymph node metastasis." (PMID 35408786, 2022).
tumor (continued). "Intracellular and extracellular HMGB1 has been implicated in tumor formation, progression, and metastasis." (PMID 35269741, 2022). "Damage-associated molecular patterns (DAMPs) such as CRT and HMGB1 induced by ICD enable the host immune activation against tumor cells." (PMID 35812418, 2022). "CXCL12 addition to tumor cells also induces the release of damage associated molecular patterns such as ATP, HMGB1 and calreticulin; in turn, HMGB1 can promote the secretion of CXCL12." (PMID 35565443, 2022). "CD24 and TIM-3 are considered negative receptors, since they inhibit the immune responses induced by HMGB1 in tumor-associated dendritic cells and macrophages, respectively." (PMID 35269471, 2022). "Then, the associations between the expression level of HMGB1 and prognostic significance with different tumours derived from TCGA and GEO databases were investigated." (PMID 35765707, 2022). "HMGB1 contributed to M1-like polarization of tumor associated macrophages (TAMs) and enhanced the sensitivity of GB cells to TMZ." (PMID 35193644, 2022). "High mobility group box 1 protein (HMGB1), a damage‐associated molecular pattern protein, is upregulated in hypoxic tumor tissues, which promotes tumor invasion and correlates with poor prognosis in HNSCC." (PMID 34964283, 2022). "The abscopal effect occurs when an irradiated tumor initiates a cascade of events with the release of damage-associated molecular patterns (DAMPs) such as high mobility group box 1 (HMGB1), adenosine triphosphate (ATP), and heat shock proteins (HSPs)." (PMID 34063642, 2021). "HMGB1 levels correlated with primary tumor progression and distant metastasis, whereas CML-HMGB1 levels were associated with primary tumor progression, lymph node metastasis, distant metastasis, and stage." (PMID 34068442, 2021). "DAMPs or TAAs released by dying tumor cells caused by radiation include not only immune enhancing elements such as calreticulin and HMGB1 but also immunosuppressive factors such as IL-10 and TGF-β." (PMID 33968889, 2021). "After killing tumor cells with chemotherapeutic drugs, tumor cells release a number of cell death-associated molecules (CDAMs), including high mobility group box 1 (HMGB1), adenosine triphosphate (ATP), calrectin (CRT), and so on." (PMID 34869005, 2021). "To validate the association between HMGB1 expression and the number of tumor-infiltrating macrophages, we examined HMGB1 expression in UTUC by IHC." (PMID 34244567, 2021). "High-mobility group box 1 (HMGB1) associated with NETs interacts with RAGE on the tumor cells, resulting in the activation of NFκB signaling pathways." (PMID 34572138, 2021). "Anti-HMGB1 therapy inhibited tumor growth, diminished the recruitment of immunosuppressive cells, and enhanced the antigen-presenting capacity of tumor-associated dendritic cells." (PMID 34943830, 2021). "More importantly, we observed that RAGE inhibition was associated with lower levels of HMGB1 in the tumor extracts treated with gemcitabine (p = 0.005) than in the mice treated with gemcitabine and the control IgGs." (PMID 33915939, 2021). "The necrotic cell death of tumor cells caused by radiotherapy or chemotherapy triggers the production of high mobility group box 1 (HMGB1), which is a damage-associated molecular pattern (DAMP) molecule, and thus can induce immune responses." (PMID 34440778, 2021). "Some of HMGB1 single nucleotide polymorphisms (SNPs) have been related to tumor progression in T2 tumor, pathologic grade 3 disease, and distant metastasis in TNBC and HER2-enriched tumors compared with luminal tumors." (PMID 34283088, 2021). "When secreted into the tumor microenvironment, HMGB1 acts as a damage-associated molecular pattern (DAMP) by interacting with cell surface receptors, including RAGE and the Toll-like receptors (TLR)." (PMID 33915939, 2021). "Tumour-secreted HMGB1 was also shown to activate primary macrophages to a tumour-associated phenotype." (PMID 33922955, 2021).